IL13 (interleukin 13)
Diseases named in the same sentence as IL13 in open-access papers (continued):
Sharing a sentence is not in itself a finding about the gene and the disease.
infection (continued). "On the other hand, anti-inflammatory cytokines interleukin-13 (IL-13), interleukin-4 (IL-4), interleukin-10 (IL-10) and transforming growth factor-β (TGF-β) appear on the fourth day after infection and ameliorate the exacerbation of inflammation and participate in the healing of lesions." (PMID 35053737, 2022). "Il5 and Il13 expression remained elevated in whole duodenal tissue at day 21 of infection, but this increase above naïve control was not statistically significant when IL-10 signalling was disrupted." (PMID 35428872, 2022). "Although we saw many changes to the lung matrisome due to infection in WT mice, we did not observe major changes in lung collagens in Il13−/− mice after infection." (PMID 34127548, 2021). "Several collagen types (notably collagens I, III, and VI) clustered together, with proteins reduced in WT mice after infection, an effect not replicated in Il13−/− mice." (PMID 34127548, 2021). "However, following treatment among children with natural infection in this cohort, PBMC stimulation in response to SWAP and SEA resulted in significant increases in the production of IL-4, IL-5, IL-10, and IL-13 compared to uninfected children." (PMID 33861768, 2021). "The low IL-13 concentrations in C57BL/6 pups did not affect arginase activity which was similar to the BALB/c pups throughout infection." (PMID 34682248, 2021). "Our data showed no increase in circulating TNF levels in LP 3% mice upon infection, and, although we have not measured IL-13 levels, studies demonstrated that the level of this cytokine is lower in the absence of IL-4." (PMID 33815321, 2021). "Indeed, following infection with Nippostrongylus brasiliensis, a helminth frequently used to study type 2 immunity, ILC2-derived IL-13 is critical for worm expulsion from the gut." (PMID 34484215, 2021). "Based on these data, we hypothesize that the presence of immunoregulatory cytokines, such as IL-4 and IL-13, and alternatively activated macrophages and MDSC during resolution of infection may play a protective role in the postnatal developing lung." (PMID 34682248, 2021). "We also failed to see IL-13 compensate for the lack of IL-4 and in fact IL-13 was lower in the lungs of IL-4−/− pups at day 30 post-infection as compared to wild type pups." (PMID 34682248, 2021). "Fibrinogen also correlated weakly with IL-13 in BSIII–IV without infection but not when infection was present (and)." (PMID 33723589, 2021). "RV-C15 infection of naïve mice increased BAL monocytes, neutrophils, eosinophils and lymphocytes, while inducing mRNA expression of IFN-γ, CXCL10, IL-17A, IL-13 and IL-5." (PMID 33968043, 2021). "The mRNA expression levels of type 1 and 2 cytokines, i.e., interferon (IFN)-γ [NM_008337], interleukin (IL)-4 [NM_021283], IL-5 [NM_010558], and IL-13 [NM_008355], were not altered by larval infection." (PMID 34081755, 2021). "However, both probiotics increased the mRNA expression of IL-1β, INF-γ, IL-13, IL-17, and TGF-β in the jejunum at seven days post infection (day 28)." (PMID 34136557, 2021). "In addition, we performed immunofluorescence staining in lung sections and found that the airways, which were highly RELM-α+ after infection in WT mice, appeared largely diminished in RELM-α expression in infected Il13−/− mice." (PMID 34127548, 2021). "IL-13, a Th2 cytokine, also showed a slight increase at 3 days after NNV infection." (PMID 33467734, 2021). "RV-C15 infection increased airway eosinophilic inflammation and mRNA expression of IL-13, Muc5ac and Muc5b in Rorafl/fl mice but not Rorafl/flIl7rCre littermates." (PMID 33968043, 2021). "ILC2s, a group of lineage negative non-antigen specific cells, produce IL-13 upon activation by the alarmin cytokines IL-25 and IL-33 during infection with helminths." (PMID 34578195, 2021).
infection (continued). "In this study, the expression of T-bet and IFN-γ1 showed a significant increase, and subsequently STAT-1 expression was up-regulated at 1 day post-infection with NNVand immuno-stimulation with KLH, whereas slight increases in IL-13 and GATA-3 expression were noted at 3 days post-NNV infection." (PMID 33467734, 2021). "Strikingly, by d7pi, IL-5+ and IL-13+ CD4+ T cell numbers did not increase in Il17a-KO mice in response to infection." (PMID 32636457, 2020). "Assays of serum samples by capture ELISA revealed no detectable levels of IL-1 or IL-13 in sera of naïve or infection controls, or in SmCB1- and SmCL3-immunized mice at any time-point following S. mansoni infection." (PMID 33207535, 2020). "During the first week following the infection we observed an increase in IP-10 and IFN-γ, however, we also observed a switch toward Th2-type responses characterized by the increase of Th2 cytokines IL-5 and IL-13 over time." (PMID 33247138, 2020). "Subsequently, we sought to examine the influence of Ss infection on the systemic levels of Type-1 (IFN-γ, TNF-α, and IL-2), Type-17 (IL-17A and IL-22), Type-2 (IL-4, IL-5, and IL-13), regulatory (IL-10) and pro-inflammatory cytokines (IL-1α, IL-1β, IL-6, IL-12, and GM-CSF) in INF and UN individuals." (PMID 33042134, 2020). "Five days of IL-13 treatment strongly downregulated ACE2 apical staining (2.4-fold, p = 0.03), which was conversely strongly increased by both acute HRV-A (2.0-fold, p = 2e−3) and HRV-C infection (1.7-fold, p = 0.02)." (PMID 33046696, 2020). "Administration of an anti-OX40L antibody during primary infection of neonatal mice resulted in reduced AHR, as well as reduced IL-5 and IL-13 levels in the bronchoalveolar lavage fluid (BALF) from mice when they were re-infected compared to mice treated with a control antibody." (PMID 32397226, 2020). "To study which factor is related to reduced fibrosis in S. japonicum-infected TCR δ KO mice, we extracted RNA from the liver tissue of the WT and KO mice at 6 weeks post-infection, and measured the mRNA transcripts of collagen, TGF-β, IL-17A and IL-13 using qRT-PCR." (PMID 32611373, 2020). "In antibiotic-treated mice, none of the infection groups had significant changes in IL-13 gene expression (unpaired t-test, p > 0.05)." (PMID 33014894, 2020). "Here, TGF-β, and not IL-13, was decreased in the KO mouse livers at 6 weeks post-infection; IL-17A was also decreased in the KO mouse livers." (PMID 32611373, 2020). "A significant number of studies from our laboratories have identified protective roles for IL-4, IL-13 and IL-4Rα signaling, not merely during primary infection with L. donovani infection, but also for effective sodium stibogluconate chemotherapy." (PMID 31475014, 2019). "Hence, we performed a time course kinetic experiment using BMDMs stimulated with IL-4, IL-13, and a combination of IL-4 and IL-13 (IL-4/IL-13) for alternative activation, followed by Mtb HN878 infection." (PMID 30941122, 2019). "Patients with prolonged arthralgia during MAYV infection show that levels of IL-1Ra, IL-6, IL-7, IL-8, IL-13, IL-17, G-CSF, IFN-γ, PDGF- α, VEGF and IL-12p70 remained elevated up to 12 months after infection." (PMID 31050676, 2019). "Further, we found the levels of IL-4, IL-10 and IL-13 were not elevated in response to rosiglitazone treatment during super-infection." (PMID 31159430, 2019). "While ILC2 production of IL-13 alone appears to be sufficient to support this macrophage population, ILC2s depend on IL-2 from CD4+ T cells to survive and mediate these effects during infection." (PMID 31072011, 2019). "We demonstrate in these studies that IL-4/IL-13 polarization increases the expression of cell surface receptors important for EBOV infection on mouse pmacs and human MDMs, resulting in enhanced Ebola GP-dependent infection in both wild-type and Ifnar-/- cells." (PMID 31825972, 2019).
infection (continued). "We found that IL-4/IL-13 enhanced in vivo infection of pmacs upon rVSV/EBOV GP challenge, but not rVSV/G." (PMID 31825972, 2019). "The phagocytic uptake of Mtb at 4 h post-infection was not affected by the knockdown of either miR-143 or miR-365 in M(IL-4/IL-13) stimulated BMDMs, excluding possible antagomiR-induced cytotoxicity or inconstant uptake due to antagomiR treatment." (PMID 30941122, 2019). "IL-13 release by ILC2 is essential for clearance of the infection since lack of IL-13 results in inefficient worm expulsion and transfer of wild-type ILC2 into IL-13-deficient mice can restore worm clearance." (PMID 29760695, 2018). "In the submerged culture, bronchial epithelial cells did not increase IP-10 production following HRV16 infection in the absence or presence of IL-13 treatment, although IL-13 treatment trended to increase IP-10 in the infected cells (p = 0.16)." (PMID 29721720, 2018). "HRV16 infection in IL-13-treated cells of both cell types did not further increase eotaxin 3 production." (PMID 29721720, 2018). "A 2.2-fold increase in the amount of Igf-I mRNA was observed upon amastigote infection, a 1.2-fold increase was observed following stimulation with IFN-γ, and an 8.7-fold increase was observed when cells were simultaneously stimulated with IL-4 and IL-13." (PMID 30150896, 2018). "Together, after infection with T. cruzi the expression of NOS2 was not impaired in the presence of high IL-13 concentrations." (PMID 30555475, 2018). "Cytokine response ratios were evaluated for patients with and without subsequent infection and only cytokine response ratios for IL5 and IL13 were significantly associated with increased risk for infection (p = 0.01 for both)." (PMID 29051761, 2017). "In contrast, in Cftr−/−mice, both types of ILC2 steadily increased throughout the infection along with the expression of the ILC2 transcription factors, Rora, and Gata3 and the production of ILC2 effector cytokines, IL-5 and IL-13." (PMID 28090087, 2017). "This augmented early inflammatory response in the absence of Il13 translated into an improved bacterial clearance from lungs 48 hr post-infection and completely prevented the systemic spread of bacteria." (PMID 28228256, 2017). "As murine lymphocytes are not responsive to IL-13, this mouse model provided an invaluable tool to investigate a role for IL-4-responsive B cells during infection with L. major." (PMID 29176972, 2017). "Upon infection of Il13−/− and WT mice with S. pneumoniae, we observed a more pronounced early (6 hr) influx of neutrophils in bronchoalveolar lavage fluid (BALF) and lung and enhanced amounts of lung CXCL1 in Il13−/− mice." (PMID 28228256, 2017). "There was a significant induction of IL-13 protein in the lungs of RSV-infected mice compared with levels seen in mock-infected mice beginning at day 4 after infection and continuing through day 8 after infection." (PMID 27156176, 2016). "Interestingly, however, IL-13 production by pre-activated OT-II cells was significantly enhanced in the presence of pDCs isolated from S. mansoni-infected livers, suggesting that pDCs might have a supporting role in shaping some aspects of the Th2 response during infection." (PMID 26657145, 2016). "We also identified differences between the responses of young and aged mice to infection, including four markers that were significantly elevated in young mice (IL-1β, IL-10, IL-13, eotaxin) but not aged or dam mice." (PMID 27936166, 2016). "Concerning the possible consequences of IL-13 reduction by BPA, it is well known that IL-13, together with IL-4, orchestrate type-2 immunity, inducing host protection, with defense mechanisms against parasites and controlling infection." (PMID 27509021, 2016). "Protection was associated with increased pulmonary type 2 cytokines IL-4 and IL-13 but not IL-33 at day 5 post infection." (PMID 26900854, 2016).
infection (continued). "Moreover, while the extent of upregulation of IL6 by infection remained similar in both breeds (~6.8 fold), overexpression of both IL10 and IL13 mRNA molecules was more profound in the resistant breed (CHB) than in CS." (PMID 27197554, 2016). "Our current findings strongly indicate that low peripheral IL-13 levels are a marker of non-patent or low egg intensity infections a facet that has not been observed in S. haematobium-infected individuals." (PMID 27152725, 2016). "Multiple cytokines in RDPs, including TNF-α, IL-8, IP-10, MCP-1, MIP-1α, IL-1ra, IL-10, G-CSF, IFN-γ, IL-4 and IL-17, reached peak value in 4 to 5 weeks after infection, whereas only IP-10 and IL-13 in SPDs did so, and lack of TNF-α in SDPs." (PMID 27830756, 2016). "Infection of DCs with wt EBOV resulted in a significant reduction of the majority of cytokines and chemokines analyzed in comparison to mock-infected DCs, with a few exceptions, including IL-4, IL-5 and IL-13." (PMID 27930745, 2016). "To allow time for this early IL-13 to induce physiologic changes in the airways, we evaluated PAS-stained sections of lungs from mock- and RSV-infected WT and TSLPR KO mice at day 6 after infection." (PMID 27156176, 2016). "Infection-induced alterations in ileal AMP expression seen in N. brasiliensis-infected WT mice, including up-regulation of Retnlb and Ang4 and down-regulation of Reg3γ, disappeared almost entirely in IL-13−/− or STAT6−/− mice." (PMID 26377648, 2015). "In vivo, infection of Kdm5bfl/fl-CD11c-Cre+ mice with RSV resulted in higher production of IFN-γ and reduced IL-4 and IL-5 compared to littermate controls, with significantly decreased inflammation, IL-13, and mucus production in the lungs." (PMID 26083387, 2015). "However, in this scenario, the ongoing CD4+ T-cell response would also produce IL-13 and data from the N. brasiliensis system suggest that the CD4+ T cell is critical to control of secondary infections." (PMID 24942690, 2014). "Infection with the YPIII-derived strains did not induce a systemic increase of IL-13 in comparison to uninfected mice, while a 2-fold rise in its levels was observed in mice infected with IP32953 and IP32953 phoP−." (PMID 25075520, 2014). "None of the increases in IL-4, IL-5, IL-9, and IL-13 in response to SEA were correlated with pretreatment infection intensity." (PMID 24357629, 2014). "In this study, expression levels of IL-4, IL-10, IL-13 and TNF-α were significantly up-regulated while the expression levels of IL-1β,IL-18,IFN-γ, IL-2, IL-15, IL-17F, IFN-α, IFN-β, IL-3 and CSF-1 were markedly decreased in PBMCs at all stages of infection." (PMID 24358317, 2013). "CD4+ T cells do not commit to the Tfh lineage until days 6–10 of infection 39, and at day 7 of H. polygyrus infection, on the cusp of Tfh-cell commitment, the numbers of IL-4 and IL-13 producing CD4+ T cells in the MLNs were equivalent in WT and ICOS−/− mice." (PMID 23319295, 2013). "However, MDM treated in vitro with IL-13 or IL-4 express DC-SIGN and, hence, can mediate HIV-1 trans infection." (PMID 24278768, 2013). "Especially the animals infected with L4 larvae showed high il13 transcription at 18 DPT, which may indicate that the initial Th1 bias shifts towards a Th2 response as the infection progresses." (PMID 24340121, 2013). "Hepatic CD8+ T cells produced neither IL-4 nor IL-13 throughout the infection although obvious IFN-γ production was observed (data not shown)." (PMID 24358216, 2013). "In addition, except for 4 of the regulatory genes (IRF4, JAK1, NFATC4 and STAT6), many of the other genes in this pathway were only transiently expressed at 2 (IL4R and PTPRC) or 4 and/or 8 (IL13, IL4 and CEBPB) weeks post-infection." (PMID 23448601, 2013). "We observed a significant population of IL-13+ CD4+ T-cells within the intestinal lamina propria early during infection in Itgb8 (CD11c-Cre) which was not apparent in control mice." (PMID 24098124, 2013).
infection (continued). "Further, we did not detect the presence of IL-4, IL-5 or IL-13 in culture supernatants at any time after infection among cells infected with MOI = 50 with LVS or SchuS4." (PMID 24324751, 2013). "Conversely, “non-healer” BALB/c mice are unable to control infection and develop a Th2 immune response characterized by the production of IL-4 and IL-13 cytokines." (PMID 24204259, 2013). "However, infection at this age increased MSC and AHR and thus the severity of AAD by inducing systemic IL-13 responses and altering lung structure." (PMID 22870337, 2012). "The concentrations of all analytes, with the exception of IL-5 and IL-13, were significantly elevated in serum at 72 hpi, supporting our hypothesis of a strong unregulated immune response following ZH501 infection." (PMID 22389738, 2012). "In contrast to what occurred in neonates, infection of infants altered hematopoietic cells to increase the severity of AAD in later-life by increasing Th2 (IL-5 and IL-13) cytokine release from MLN cells, MSC numbers, transpulmonary resistance and IL-13 production in the lung." (PMID 22870337, 2012). "In the present study, there was a rapid shift from a Th1 immune response characterised by the expression of IFNγ and IL-1β genes to a regulated Th2 immune response characterised by the expression of IL-13, IL-10, TGFβ, and FOXP3 genes by seven days post infection (dpi) in the carrier lambs." (PMID 21385411, 2011). "In untreated rabbits, most of these genes were progressively induced by Mtb infection from 4 to 8 weeks, and many had reached a plateau (IFN-γ, IL13, IL6, MIF, CCL4, NFκB, APRIL, TLR2, RAB7 and LAMP2) or were even reduced (IL10, CXCR3, GMCSF and PI3K3) by 12 weeks post-infection." (PMID 21949656, 2011). "This indicates that there are other mechanisms rather than changes in cytokine responses or in T cell phenotype that result in reduced infection in the absence of IL-13." (PMID 21573182, 2011). "Following infection with 200 Trichuris eggs (high dose), wild-type C57BL/6 (WT) mice develop a polarized CD4+ Th2 cell response characterized by high levels of IL-4, IL-5 and IL-13." (PMID 21573179, 2011). "Collectively, these data demonstrate a lack of CD4+ T cell involvement and a novel role for IL-13 in innate responses to infection." (PMID 21573182, 2011). "Collectively these data demonstrate that upon infection with L. mexicana, initial lesion growth in BALB/c mice is dependent on non-T cell population(s) responsive to IL-4/IL-13 while progressive infection is dependent on CD4+ T cells responsive to IL-4." (PMID 21245915, 2011). "We observed that IL-10 expression was up-regulated 4- fold at 5 h and 90-fold at 24 h post-infection (p.i.), while expression of IL-4, IL-13 and another immunosuppressive cytokine, TGF-β, were not significantly altered at both time points (data not shown)." (PMID 19816558, 2009). "In viewof the importance of IL-13, or of the shared receptor between IL-4and IL-13, our data do not allow us to exclude the possibilitythat IL-4 synergizes with IL-13 to downregulate CXCL-8 productionduring infection with M. bovis BCG." (PMID 16864907, 2006). "In fact, elevated levels of IL-13 were observed in whole lung homogenates as early as 5 hours post-infection (data not shown) and were again observed in adult lungs on protocol day 69 suggesting that IL-13 is being chronically produced." (PMID 16893457, 2006). "Importantly, although p43 is not immunogenic during natural infection, vaccination with p43 in an alum adjuvant resulted in parasite ejection, thought to be due to the blockade of p43-mediated immunomodulation of IL-13." (PMID 40302223, 2025). "However, expression of Alox12, Alox12e, Alox8, Alox12b, Il13rα1, Il4rα, Il2rg, and Il13 were not altered following Hpb infection." (PMID 40490052, 2025). "Although we could not reliably measure IL‐4, we found IL‐13 in the cavity fluid to be strongly induced by infection and not to be affected by CD154 blocking." (PMID 41388224, 2025).